IL6 (interleukin 6)
Diseases named in the same sentence as IL6 in open-access papers (continued):
Sharing a sentence is not in itself a finding about the gene and the disease.
COVID-19 (continued). "We hypothesize that IL-6-STAT3 signaling is a promising therapeutic target for the cytokine storm in COVID-19, because IL-6 is a major STAT3 stimulator, particularly during inflammation." (PMID 33014208, 2020). "A dysregulated immune response—characterized by decreased T-cell counts, increased inflammatory cytokines and extra-pulmonary systemic hyperinflammation syndrome—is principally responsible for inducing critical pulmonary failure observed in COVID-19 and largely driven by interleukin-6 (IL-6)." (PMID 33194450, 2020). "A diet rich in such compounds may help patients with COVID-19 to reduce their inflammation due to the hyper-activation of cytokines such as TNFα, IL-1β, IL-6, and IL-8." (PMID 33322757, 2020). "Controlled studies are needed to determine whether cytokine blockade and in particular blockade of IL-6, confers benefit to persons with COVID-19." (PMID 33089038, 2020). "The remainder of fecal cytokines analyzed (IL-1β, IL-1ra, IL-6, IL-8, IL-17, TNFα) were not significantly different in COVID-19 patients compared to controls nor associated with severity of disease." (PMID 32909002, 2020). "Treatment of these whole blood samples with the small molecule R848, a mimic of TLR7 and TLR8 activation by single strand RNA, increased the percentage of IL-6+ blood monocytes, with significantly higher levels in samples from COVID-19 patients compared to healthy controls." (PMID 32503877, 2020). "Some authors have also reported a role for IL-6 and IL-10 in monitoring COVID-19 patients." (PMID 32397174, 2020). "Considering that headache patients also had shorter COVID-19 disease evolution, their lower and more stable IL-6 levels may indicate that inflammation may be kept at a more localised level." (PMID 33146036, 2020). "Older age and higher levels of C-reactive protein, procalcitionin, interleukin-6, and lactate might predict COVID-19 progression." (PMID 33239109, 2020). "Considering the multiple immune modulatory mechanisms of MSCs, a gradual decline of IL-6 level might turn out to be a biologically relevant surrogate marker of the efficacy of MSCs treatment in patients with COVID-19." (PMID 32855385, 2020). "IL-6, in particular, has been highly implicated in CRS and COVID-19 severity, and inhibition of IL-6/IL-6R activity may lead to improved patient outcome, increasing its desirability as a target." (PMID 33733182, 2020). "Elevated levels of CRP, TNF-, and IL-6 are involved in COVID-19 pathogenesis and may act as potential biomarkers for the management of the severity of the disease." (PMID 33244370, 2020). "A range of strategies have been proposed and are being evaluated to dampen hyper-inflammation in COVID-19 such as corticosteroid therapies, antibodies against IL-1 or IL-6, treatments interfering with the interferon pathway and anti-tumor necrosis factor therapies." (PMID 32922409, 2020). "Therefore, it is necessary to determine the persistence of high IL-6 levels in recovered COVID-19 patients." (PMID 33041985, 2020). "Our work showed that IL-6 and IL-8 could be combined used as biomarker for different disease stages of COVID-19 patients." (PMID 33488599, 2020). "Since elevated IL-6 levels were consistently reported during COVID-19 and were correlated with higher mortality in these patients, IL-6 might serve as a predictive biomarker for COVID-19 severity." (PMID 32548750, 2020). "IL-6, in particular, has been documented for its potent role in immune dysregulation in COVID-19." (PMID 33120941, 2020). "Thus, taking together all our findings, we can suggest that steroids seem to be able to limit the secretion of IL6 in severe COVID-19." (PMID 33198751, 2020). "As previously reported, IL-6 levels were also elevated in COVID-19-infected patients." (PMID 32817460, 2020). "IL-6 showed a significant kinetics changes in COVID-19 cases with fatal outcome." (PMID 33195318, 2020).
COVID-19 (continued). "As a candidate for potential use in COVID-19, rapamycin may prevent progression to severe forms of COVID-19 by downregulating the IL-6 pathway and reducing the number of senescent T-cells through the mTOR-NLRP3-IL-1β axis at the early stage of cytokine storms." (PMID 33269102, 2020). "IL-6 plays a central role as a mediator of toxicity in the cytokine release syndrome CRS/cytokine storm, which is associated with severe cases of SARS-CoV-2 infection/COVID-19." (PMID 32668803, 2020). "Besides IL-6, which has been reported as a potential biomarker for COVID-19 patients, we found that both IL-6 and IL-8 serum levels were elevated in COVID-19 patients with severe diseases." (PMID 33488599, 2020). "Among all these candidate target cytokines, IL-6 seems to be one of the best choices, particularly for COVID-19 patients with RA: from the aspects of either availability of the products or the current evidences supporting the benefits in treating both of the diseases." (PMID 32562070, 2020). "Similarly, a retrospective, multicentre cohort study containing 191 COVID-19 patients also found increased ferritin and IL-6." (PMID 32519302, 2020). "COVID-19 can involve the respiratory tract determining a mild or highly acute respiratory syndrome due to the production of pro-inflammatory cytokines, such as interleukin (IL)-1beta and IL-6." (PMID 32471083, 2020). "Besides Th17 responses, patients diagnosed with COVID-19 showed marked rise of the Th1 subset (inflammatory cytokines IL-1β, IL-6, and IL-12) for more than 2 weeks after the infection onset." (PMID 32765279, 2020). "Our results, together with other study findings, suggest that IL-6 could serve as a useful marker to guide tocilizumab therapy in COVID-19." (PMID 32727465, 2020). "Similarly, we detected significantly elevated IL-6 levels in COVID-19 patients compared to healthy controls." (PMID 33123154, 2020). "Our data suggest that for COVID-19 patients requiring mechanical ventilation, IL-6 blockade alone may be insufficient; other interventions are necessary." (PMID 33089038, 2020). "In the present study, IL-2R, IL-6, TNF-α, and hs-CRP were significantly higher than the normal range and higher in the AKI group, and PCT more than 0.1 ng/mL was found to be associated with COVID-19-related AKI." (PMID 32850917, 2020). "COVID-19 has worse outcomes in the obese and diabetic populations, likely because these patients are already in a proinflammatory state at baseline due to elevated levels of interleukin 6 (IL-6) from insulin and leptin resistance." (PMID 32708430, 2020). "In terms of laboratory tests, we noted that most of COVID-19 patients presented lymphopoenia, decreased level of lymphocyte subsets and elevated levels of infection related biomarkers (including IL-6, ESR and lactate dehydrogenase), which was consistent with recent reports." (PMID 33256876, 2020). "At 24h after the first clinical signs of COVID-19, interleukins (IL-1α, IL-1β, IL-6, IL-10), and IFNs (IFN-α2, IFN-β1, IFN-II) are significantly elevated, but the cellular sources of those cytokines are probably more epithelial and innate cells than T lymphocytes." (PMID 33335532, 2020). "It is suggested that the higher release of interleukin-6 (IL-6) during this initial immune response may suppress T lymphocyte activation, which would explain the presence of lymphopenia in COVID-19 patients." (PMID 33122784, 2020). "Considering its close relation to ARDS, and also that neutrophilia, high levels of IL-1β, IL-6, and D-dimer are poor outcome predictors in COVID-19, some authors suggest that NET may play a major role in its pathogenesis." (PMID 32962761, 2020). "Importantly, we found significantly higher expression of secreted IL-6, as have others, especially in ICU patients, underscoring the rationale for testing anti-IL-6 or anti-IL-6R antibodies in severely ill COVID-19 patients." (PMID 32829467, 2020).
COVID-19 (continued). "If confirmed, therapeutic consideration should be given to inhibiting both IL-6 and GC activity in most of the patients with COVID-19 exhibiting this phenotype (high IL-6, low IFN signaling, and profound cytopenias) versus the small proportion of patients with a true cytokine storm phenotype." (PMID 33187979, 2020). "Finally, before and after application of DYY, the core target gene IL6 of COVID-19 patients was detected by ELISA to validate the clinical effects." (PMID 32536965, 2020). "This is in accordance with other pro-inflammatory cytokines that were reportedly increased in the peripheral blood of patients with COVID-19, such as the Th-17 inducing cytokine IL-6, IL-10, IL-2 and the Th1 signature cytokines interferon gamma (IFN)-γ and tumor necrosis factor (TNF)-α." (PMID 32512702, 2020). "Both methods have shown IL-6 up-regulation in these severe and critical COVID-19 patients." (PMID 32350134, 2020). "Besides using IL-6 as a therapeutic target for COVID-19, an inhibitor against IL-1 has also been subjected to investigation for its effect upon disease progression." (PMID 32595947, 2020). "This supports the early application of IL-6 blockade treatment for patients with COVID-19." (PMID 33384605, 2020). "Increased IL-6 level may be an independent risk factor for disease severity and in-hospital mortality and dynamic IL-6 changes may serve as a potential predictor for lung injury in Chinese COVID-19 patients." (PMID 32765283, 2020). "Decreased expression and secretion of IL-1β and IL-6 was observed in the COVID-19 patients." (PMID 33708109, 2020). "Interestingly, IL-6, reported to be increased in COVID-19 patients, is one of the major activators of JAK/STAT signaling." (PMID 33489899, 2020). "The role played by IL-6 in COVID-19-related inflammation is confirmed by the fact that patients with higher circulating levels of IL-6 and other inflammatory cytokines, such as persons suffering from Down syndrome, are at a higher risk of developing more severe forms of COVID-19 infection." (PMID 32718086, 2020). "Inflammation is closely related to severity of COVID-19, and IL-6 and TNFα might be promising therapeutic targets." (PMID 33349241, 2020). "The presence of high plasma IL-6 levels in COVID-19 patients may justify the use of tocilizumab, a monoclonal IL-6 receptor antibody, and offer a protective effect against the cytokine storm." (PMID 33391014, 2020). "In support of this hypothesis, patients with more-severe COVID-19 had higher serum levels of IL-2R, IL-6, IL-10, and tumor necrosis factor alpha (TNF-α) than patients with milder disease." (PMID 32616514, 2020). "Although the exact mechanisms remained unknown, the so-called “IL-6 amplifier” may explain the CRS in severe COVID-19 patients." (PMID 33195318, 2020). "Whether the occurrence of a cytokine release syndrome integrating elevated IL-6 levels should be a prerequisite for the administration of TCZ in COVID-19 patients remains to be fully elucidated in larger future studies." (PMID 33169088, 2020). "Indeed, in COVID-19, very critical patients display a cytokine storm syndrome with an increased secretion of interleukin (IL)-6, IL-1β, IL-17, IL-8, tumor necrosis factor (TNF)-α, interferon (IFN)-γ and other pro-inflammatory mediators." (PMID 32708322, 2020). "Likewise, proteomic profiling approaches and targeted analysis of plasma proteins have shown high IL-6, IL-10, IL-8 and IFNγ levels in many COVID-19 patients." (PMID 33239683, 2020). "In addition, the good predictive capability of IL-6 for disease severity and prognosis in COVID-19 patients, assessed by the ROC curves (AUC > 0.75), provided further evidence regarding its predictive function." (PMID 32765283, 2020). "In conclusion, IL-6–mediated inflammation in COVID-19 might affect Trp catabolism, as observed in autoimmune diabetes and other experimental conditions." (PMID 32636755, 2020).
COVID-19 (continued). "Many reports have presented the clinical efficacy of IL-6 blockade in treating ∼1600 severe/critically ill COVID-19 patients using the anti-IL-6R monoclonal antibodies tocilizumab, or sarilumab, and IL-6 neutralizing antibody siltuximab." (PMID 32766256, 2020). "In addition, biopsy of lung tissues of COVID-19 patients shows upregulation of interleukin-6 (IL-6), tumor necrosis factor-α, intercellular adhesion molecule-1, and caspase-1 expression." (PMID 33537347, 2020). "The significantly elevated levels of IL-6 in cancer patients with COVID-19 indicated that IL-6 blockade may be effective for this specific subgroup of patients." (PMID 32522278, 2020). "When IL-6 was over 24.3 pg/ml, the severity of COVID-19 could be predicted with sensitivity and the speciality of 73.3 and 89.3%, respectively." (PMID 33195318, 2020). "A cytokine storm has been identified as a pathogenic mechanism for the deterioration of critically ill patients with COVID-19 by careful examination of circulating cytokines; in particular, the cytokines IL-1β and IL-6 have been recognised as leading to lung inflammation." (PMID 32992282, 2020). "Additionally, the IL-6 trans-signaling‒PAI-1 axis is also critical for the pathogenesis of COVID-19–induced CRS, which leads to endotheliopathy and coagulopathy." (PMID 32826331, 2020). "Anti-IL6 inhibitors are among the therapeutic armamentarium for preventing the fatal consequences of acute respiratory and multi organ failure in around 20% of the COVID-19 infected patients." (PMID 32938496, 2020). "IL-6 has assumed a central position in the COVID-19-related cytokine storm." (PMID 33142844, 2020). "This indicates that lymphopenia may be driven, in part, by the cytokine storm which occurs during COVID-19, and consistent with this hypothesis, high circulating levels of IL-6 and IL-8 correlate with lymphopenia in COVID-19 patients." (PMID 33302366, 2020). "Furthermore, lL-8 levels correlated better than IL-6 levels with the overall clinical disease scores at different stages of the same COVID-19 patients." (PMID 33488599, 2020). "Elderly patients with COVID-19 often present with a severe dysregulation of pro-inflammatory cytokines, such as IL-6 and IL-1 β, which may result in worse outcome." (PMID 32849623, 2020). "Because complement participates in various inflammatory skin diseases, complement may be produced in response to IL-6 in COVID-19 patients, promoting the cutaneous skin disorders characteristic of COVID-19." (PMID 32922297, 2020). "As for IL-6, it was reported that their levels were unchanged in moderate COVID-19 cases compared with mild cases, while other reports revealed that elevated IL-6 levels were observed during COVID-19 progression." (PMID 33537060, 2020). "For example, IL-6 overexpression and oxidative stress lead to increased fibrinogen processing and fibrin levels which, in turn, interacts with NET’s facilitating coagulation phenotypes, contributing to the COVID-19-associated coagulopathy and shock." (PMID 33003552, 2020). "Interestingly, a group of disease-modifying anti-rheumatic drugs (DMARDS), including HCQ and IL6 inhibitors such as tocilizumab, was also proposed as a possible therapeutic option to treat COVID-19 patients." (PMID 32923679, 2020). "Moreover, A clinical study of 123 patients with COVID-19 showed that the percentage of patients with IL-6 above normal is higher in the severe group." (PMID 32754890, 2020). "The levels of IL-6 were low in most of the COVID-19 patients with mild symptoms and were elevated in patients with severe symptoms, which therefore may be used as a biomarker for severe COVID-19 patients." (PMID 33488599, 2020). "Increased cytokine levels, including those of IL-6, have also been reported in COVID-19 patients." (PMID 32640723, 2020). "In addition, some single case reports supporting the use of IL-6 inhibitors in severe COVID-19 have been published." (PMID 32655577, 2020).
COVID-19 (continued). "The level of IL-6 is positively correlated with the severity of COVID-19 symptoms." (PMID 32530389, 2020). "In two severe cases of COVID-19, lung injuries and cavities were filled with macrophages and neutrophils, where a fibrinous exudate could be detected, along with IL-6, TNF-α, and PD-L1 and a decrease in lymphocytes." (PMID 33324210, 2020). "Hence, we would like to report our clinical experience of the management of ARDS and hyperinflammation with the IL-6 inhibitor tocilizumab in patients with critical COVID-19." (PMID 33510989, 2020). "Moreover, monocyte HLA-DR is downregulated in severe COVID-19 patients, with expression patially restored by an IL-6 inhibitor." (PMID 33101306, 2020). "In our study, only serum IL-6 level has been quantified in some of the COVID-19 patients." (PMID 32737627, 2020). "In keeping with an exhaustion phenotype, NK cells in COVID-19 patients are functionally impaired, which could be explained by hyperinflammation, particularly the persistent elevation of IL-6 in COVID-19 patients." (PMID 34192268, 2020). "This pathophysiological process, which is supported by many studies, suggests that higher IL-6 levels may be an important predictor of COVID-19 severity." (PMID 32765283, 2020). "Interleukin-6 seems to play a crucial role in the dysregulated inflammatory response in COVID-19, therefore tocilizumab, a monoclonal antibody directed against interleukin-6, might improve clinical outcome." (PMID 32781614, 2020). "That reviewshowed how IL-6 increases the severity of COVID-19 by upregulating angiotensin-converting enzyme 2 (ACE2) receptors and induction of macrophage cathepsin L. Cathepsin L mediates the cleavage of the S1 subunit of the coronavirus surface spike glycoprotein." (PMID 33142828, 2020). "Emerging evidence indicates that there are potential benefits when managing the cytokine storm in COVID-19 patients by administering steroids, IL-6/IL-6-receptor (IL-6R) blocking antibodies, TNF inhibitors, IL-1 antagonists, and Janus kinase inhibitor (JAK) inhibitors." (PMID 33072097, 2020). "Whether an up-regulation of IL-6 and GM-CSF could be beneficial or harmful for patients with COVID-19 is difficult to predict based on the current knowledge." (PMID 33634100, 2020). "IL-6 is the main mediator of cytokine storm, and based on a meta-analysis of studies of COVID-19 patients, it is clear that the most severe cases exhibited elevated levels of IL-6, but those levels were 10–200 times lower than those seen in non-COVID-related ARDS." (PMID 33193418, 2020). "Notably, nicotine inhibits TNF, IL-1 and IL-6, which are increased in patients with COVID-19 and are involved in the cytokine storm, leading to rapid deterioration." (PMID 32782493, 2020). "IL-6 is a key biomarker for COVID-19-related cytokine storms and has shown an inverse correlation with impaired immunity; T-cell numbers were negatively correlated to the concentrations of serum IL-6, IL-10, and TNF-α." (PMID 33614744, 2020). "Furthermore, the IL-8 levels correlated better than IL-6 with the overall clinical disease scores at the different time points in the same COVID-19 patients, which can therefore be used as a disease prognosis biomarker." (PMID 33488599, 2020). "Increased IL-6 can also explain the speculative cardiac microvascular abnormalities in patients with COVID-19." (PMID 32661796, 2020). "Therefore, immune checkpoint inhibitors combined with IL-6/IL-6R-specific antibodies are expected to be a new hope for COVID-19 patients." (PMID 33240265, 2020). "Studies have shown increased amounts of cytokines, such as IL-1β, IL-1ra, IL-6, TNF-α, IL-7, IL-8, IL-9, IL-10, FGF basic, G-CSF, GM-CSF, IFN-γ, IP-10, MCP-1, MIP-1a, MIP-1b, in the serum of COVID-19 patients, and the cytokine storm was associated with disease severity." (PMID 32426374, 2020). "Increased IL-6 is an early indicator of cytokine release syndrome in COVID-19 patients." (PMID 32848776, 2020).